CYP27B1 (cytochrome P450 family 27 subfamily B member 1)
Diseases named in the same sentence as CYP27B1 in open-access papers (continued):
Sharing a sentence is not in itself a finding about the gene and the disease.
tumor (47 papers, 2010 to 2026). "A study conducted on an Asian population (from China) with 153 tumor samples (NSCLC) found that high CYP27B1 expression was associated with better OS (p = 0.018)." (PMID 36986255, 2023). "On the other hand, another study carried out in an Asian population (from China), with 153 (NSCLC) tumor samples, where a better overall survival (p = 0.018) was associated with a high CYP27B1 expression." (PMID 34836039, 2021). "Wild type rs58915677 and rs2229103 caused a decrease in CYP27B1 level in this tumor." (PMID 32197412, 2020). "Several studies have demonstrated that CYP27B1 gene is underexpressed in tumor tissues including PTC, especially in metastases." (PMID 37991208, 2024). "27-HC synthase CYP27A1 is highly expressed in M2 TAMs derived from breast cancer in mice, whereas the 27-HC catabolic enzyme CYP27B1 is expressed at low levels in tumor cells, leading to the accumulation of 27-HC in tumor tissues." (PMID 37004014, 2023). "Although tumor cells are known to express CYP27B1 at varying levels (and produce 1,25(OH)2D3), conventionally, in vitro studies of vitamin D activity utilize 1,25(OH)2D3 to avoid variation in local production across models." (PMID 32183160, 2020). "In C57BL/6 mice bearing E0771 tumors which were fed with the vitamin D-deficient diet and injected with calcitriol (100 IU+cal), we observed an increase in the level of CYP27B1 with an increase in CYP2R1 in tumor tissue." (PMID 33172201, 2020). "Mir-195 has been shown to target Bcl-2, inducing apoptosis, and target FASN, HMGCR, ACACA and CYP27B1 in hormone-receptor positive breast cancer cell lines, suppressing tumour growth, EMT, invasion and metastasis." (PMID 31077182, 2019). "It was reported that the mRNA expression and/or 1α-hydroxylase activity of CYP27B1 tend to decline during the progression of tumour development and the acquisition of higher malignant characteristics in prostate cancer." (PMID 29899561, 2018). "In the present study, we analyzed the association between the immunohistochemically-evaluated VDR and CYP27B1 levels and clinical outcomes and tumor behavior." (PMID 26501255, 2015). "A similar trend was observed for CYP27B1 immunostaining and the grade of tumor compartments in metastases (r=−0.6009, p<0.0001)." (PMID 25501638, 2015). "The CYP27B1 level was decreased in pathologic tissues in comparison to normal epithelium and was inversely correlated with tumor grade." (PMID 25501638, 2015). "The expression of CYP27B1 was positively correlated with a lower proliferation rate, lower dynamism of tumor growth and tumor infiltrating lymphocyte response." (PMID 25501638, 2015). "Seven single nucleotide polymorphisms (SNPs) were genotyped, the expression of CYP27B1 and CYP24A1 were measured in 153 tumor samples and their associations with genotypes and patient survival were also analyzed." (PMID 25544771, 2015). "Blockage of versican V1 by shRNA knockdown, in tumor cells, inhibited TLR2/6, VDR, Cyp24, Cyp27B1, and hCAP18/LL-37 induction, as well as tumor cell proliferation and invasiveness." (PMID 23424670, 2013). "Regarding CYP27B1 expression, 44.6% of cases were positive (123 out of 276 samples), whereas 53.7% of cases (151 out of 281 tumours) presented positivity for CYP24A1." (PMID 20831823, 2010). "To determine whether chromosomal looping would change CYP27B1 transcription, we examined the RNA and protein expression of CYP27B1 in tumor cells and found that it was significantly higher than that in normal ARPE19 cells." (PMID 39394698, 2024). "Thus, the pro-inflammatory tumor microenvironment is proposed to be a potential factor that reduces CYP27B1 level during tumor progression." (PMID 34208589, 2021). "Rs3782130 is present within the 3′ end of the promoter and this location may influence the CYP27B1 gene transcription process, as was demonstrated by the lower gene transcription rate in tumor cells." (PMID 32197412, 2020).
tumor (continued). "An unexpected result was renal Cyp27b1 gene expression upregulation by the vehicle (C2), which we believe might reflect reduced systemic calcitriol levels, consistent with the increased tumor volume observed in this group." (PMID 31698751, 2019). "This change in CYP27B1 expression and vitamin D metabolism in immune cells may contribute to the immune-suppressive tumor microenvironment." (PMID 29657326, 2018). "It was observed a parallel increase of VDR and CYP27B1 mRNA during early tumor progression." (PMID 30719023, 2018). "In high-grade undifferentiated tumour areas expression of CYP27B1 is decreased." (PMID 27187375, 2016). "However, it seems that the tumours influenced the renal metabolism of 1,25‐D3 as CYP27B1 expression tended to be lower in the kidneys of mice harbouring CYP24A1‐overexpressing xenografts." (PMID 26238339, 2016). "CYP27B1 staining in tumor cells was positively correlated with TILs (r=0.2356, p=0.489)." (PMID 25501638, 2015). "Furthermore, CYP27B1 expression was negatively correlated with tumor cell modeling of their microenvironment." (PMID 25501638, 2015). "Therefore, it is likely that disturbances in CYP27B1 expression can affect tumor development and progression." (PMID 25501638, 2015). "Furthermore, our results suggested that induction of VDR, Cyp24, Cyp27B1 and hCAP18/LL-37 requires macrophageTLR2/6 activity in tumor microenvironments." (PMID 23424670, 2013). "A second, distinct mechanism involves dysregulated production of 1,25-dihydroxyvitamin D. Tumor cells and tumor-associated macrophages may aberrantly express 25-hydroxyvitamin D3-1α-hydroxylase (CYP27B1), which is not suppressed by PTH or serum calcium." (PMID 41287694, 2025). "When the tumor is poorly differentiated, expression of CYP24A1 is increased and that of CYP27B1 is reduced." (PMID 36986255, 2023). "In breast tissues, it has been shown that with tumor progression, there was an increase in 1,25(OH)2D 24-hydroxylase (CYP24A1) expression and a decrease in CYP27B1 expression." (PMID 35743729, 2022). "When the tumor is poorly differentiated, there is greater expression of CYP24A1 and reduced expression of CYP27B1." (PMID 34836039, 2021). "Clearly, VDR activation in tumors requires ligand, which depends on the patient's overall vitamin D status as well as the relative activity of CYP27B1 and CYP24A1 within individual tumor cells." (PMID 34950835, 2021). "To examine if the SNPs in CYP27B1 and CYP24A1 affect their mRNA expression, we compared levels of mRNA expression by the genotypes of CYP27B1 and CYP24A1 in 153 tumor samples." (PMID 25544771, 2015). "CYP27B1 and CYP24A1 expression were significantly different between tumor and normal tissues in NSCLC." (PMID 25544771, 2015). "Based on the understandings, we performed RT-qPCR to assess the expression of CYP27B1 and CYP24A1 in lung tumor and non-tumor tissues." (PMID 25544771, 2015). "Results from mRNA expression analysis show that transcriptional activities of CYP27B1, CYP24A1 and COX-2 are significantly elevated in cancerous lesions compared to mucosal tissue outside of the tumor area." (PMID 24213465, 2012). "CYP27B1 expression is enhanced in high- to medium-differentiated human colon tumours as compared to tumour-adjacent normal mucosa or colon mucosa from non-cancer patients." (PMID 27187375, 2016). "The reduced expression of CYP27B1 was found in tumor cells, but its expression did not correlate with pT stage, presence of metastasis, tumor grade, mitotic activity or OS." (PMID 26501255, 2015). "Levels of CYP27B1 and CYP24A1 expression in tumor tissues were analyzed in 153 NSCLC patients." (PMID 25544771, 2015).
tumor (continued). "Concerning CYP27B1 expression, we have encountered positive staining in 66.4% of the cases (91 out of 137 samples); whereas CYP24A1 expression was observed in 56.0% of the tumours (70 out of 125 cases)." (PMID 20831823, 2010). "We have, as yet, no full understanding of what is happening to CYP27B1 in this type of tumor." (PMID 32197412, 2020). "Additional open questions are whether the levels of VDR, CYP27B1 and CYP24A1 and ROR in the tumor cells can also serve as reliable prognostic factors and in what way the level of VDR may affect the efficiency of vitamin D in inhibiting the tumor growth and aggressiveness." (PMID 31235702, 2019). "Therefore, increasing CYP27A1 and CYP27B1 expression and decreasing CYP24A1 production may be beneficial for inhibiting tumor growth." (PMID 30157901, 2018). "However, lack of correlation between CYP27B1 expression, a required step of vitamin D activation, and tumor progression and OS raises additional possibilities." (PMID 26501255, 2015). "Compared to non-tumor tissues, CYP27B1 mRNA expression was significantly lower in tumor tissues (p<0.001), and the expression of CYP24A1 was significantly higher in tumor than in non-tumor tissues (p<0.001)." (PMID 25544771, 2015). "Tumor formation in the skin after UVB radiation or the application of chemical carcinogens also appears to be at least partially independent of 1,25(OH)2D in that Vdr null mice develop such tumors after these challenges, but mice lacking Cyp27b1, the enzyme producing 1,25(OH)2D, do not." (PMID 34950833, 2021).
infection (31 papers, 2013 to 2025). The state of being infected such as from the introduction of a foreign agent such as serum, vaccine, antigenic substance or organism. "METTL1, METTL21B, and CYP27B1 involve in vitamin D‐mediated antibacterial activity, which is a key signaling associated with infection." (PMID 38020709, 2023). "In response to injury or infection, keratinocytes upregulate CYP27B1 and VDR, leading to increased local production of active vitamin D, which in turn induces CAMP expression, thereby strengthening cutaneous immunity." (PMID 40649943, 2025). "This was also evident 48 h post-infection with a mean increase in the relative expression fold change of 10.02 ± 0.95 (p-value < 0.001) for CYP27B1, and 3.37 ± 0.71 (p-value < 0.05) for CAMP compared to the control, and the MAP-infected only groups." (PMID 38732603, 2024). "At the 48 h post-infection time point, there was an increased relative expression of CYP27B1 and VDR (1.62 ± 0.32 and 1.27 ± 0.34, respectively) and a decreased relative expression of CAMP (0.29 ± 0.15)." (PMID 38732603, 2024). "Calcifediol treatment also reversed MAP effects at 48 h post-infection, with a decreased expression of both CYP27B1 and VDR and an increased relative expression of CAMP." (PMID 38732603, 2024). "In this study, we sought to determine if IL-27 modulates Cyp27B1 and hCAP levels in response to infection with M. tuberculosis." (PMID 36863206, 2023). "CYP27B1, the 25‐hydroxyvitamin D 1α‐hydroxylase, leads to production of active vitamin D3 at sites of infection, which is critical for the TLR2/1‐induced antimicrobial activity in macrophages infected with Mycobacterium tuberculosis." (PMID 38020709, 2023). "This study aimed to evaluate the vitamin D contribution in the expression of VDR and CYP27B1, involved in the conversion of an inactive to an active form of vitamin D in the infected macrophages using M. tuberculosis as an infection model." (PMID 35204769, 2022). "In cytotoxic T lymphocytes (CTL) as well, VDR is upregulated in case of infection, and CYP27B1 is always expressed; however, the effects of the vitamin on the proliferation, differentiation, and functions of these cells remain unelucidated." (PMID 35408981, 2022). "Conversely, Cyp27B1 and Cyp24A1 expression was higher at day 2 and day 4 post-infection than in the uninfected lung." (PMID 35893921, 2022). "Following skin injury or infection, 25(OH)D3 is hydroxylated by the enzyme cytochrome p450 27B1 (CYP27B1) to 1,25(OH)2D3." (PMID 32947991, 2020). "Following infection of monocytes, total RNA was isolated, then CYP27B1 mRNA expression was assessed by qPCR." (PMID 30300363, 2018). "At 24 h post-infection, there was a powerful upstroke in the relative expression of CYP27B1 and CAMP in MAP-infected THP-1 macrophages following TLR2 siRNA transfection with an average increase of 5.55 ± 0.82 and 24.47 ± 6.41 folds, respectively (p-value < 0.01)." (PMID 38732603, 2024). "Conversely, the differential effect of Cyp27B1 could be due to the location of the infection in the gut versus the lung." (PMID 35893921, 2022). "Indeed, both VDR and CYP27B1 are expressed in almost all immune cells, and their expression is modulated by the presence of an infection." (PMID 35408981, 2022). "Cyp27B1 expression was significantly lower in the day 4 than the day 2 post-infection lung." (PMID 35893921, 2022). "Despite the downregulation of autophagy markers observed by 7 d post-infection, CYP27B1 and VDR were still significantly upregulated indicating that TLR8 is still sufficiently engaged at these late time posts post-infection in the absence of significant cytotoxic effects (P > 0.05)." (PMID 26115100, 2015). "Downregulation of CYP27B1 by 1,25(OH)2D3 was significantly different than LPS stimulation alone or coupled with 25(OH)D3 treatment, in agreement with observations made in the present study for treatment with either form of vitamin D3 following infection of MDMs with live MAP." (PMID 35111692, 2021).
infection (continued). "Similar to helper T cells, CTLs also express CYP27B1, and local conversion of 25(OH)D into 1,25(OH)2D can stimulate activation of VDR in response to infection and mitogenic stimuli." (PMID 41041128, 2025). "Treatment with calcifediol resulted in the reversal of these gene expression trends with an upregulation of CYP27B1 and VDR expression and downregulation of CAMP expression 24 h post-infection." (PMID 38732603, 2024). "MAP infection was noted to exert the same upregulation effects on CYP27B1 and CAMP expression after 48 h of infection and treatment with SB 203580." (PMID 38732603, 2024). "The discovery of the Vitamin D receptor (VDR) and cytochrome P450 27B1 (CYP27B1) enzyme expression on immune cells has driven exploration into whether the active metabolite of vitamin D, 1,25 dihydroxyvitamin D3 [1,25(OH)2D3] (VitD3), has immunoprotective properties in the context of infection." (PMID 32318074, 2020). "One study suggested that infection with respiratory syncytial virus (RSV), a respiratory virus closely related to hMPV, increased the transcriptional expression of both CYP27B1 and CAMP in human tracheobronchial epithelial (hTBE) cells." (PMID 29780383, 2018). "Consistent with its role in the innate immune response, both the enzyme that converts vitamin D to its active form (CYP27B1) and its receptor (VDR) are upregulated in response to any of the infections (pattern "All")." (PMID 26586179, 2015). "In up-regulated genes of head kidney samples, 2 genes respond to infection by D. pseudospathaceum-clone I (HYAL2, PRF1), 3 to clone XII (RGCC, CYP27B1, CCR9) and 6 to the clone mix treatment (ITGA5, SIX1, ATP1B3, MEF2C, MLF1, MYLPF)." (PMID 25254967, 2014). "In the present study, levels of CYP24A1 and CYP27B1 were not affected by infection status, except for lower CYP27B1 expression for subclinical cows compared to clinicals." (PMID 35211544, 2022). "The expression of the Vdr, Cyp27B1, Cyp24A1 was not different in D− and D++ mice at day 6 post-infection." (PMID 35893921, 2022). "Furthermore, the infection significantly upregulated the expression of the VDR and CYP27B1 relative to uninfected macrophages, and this overexpression was not affected by high glucose concentrations." (PMID 35204769, 2022). "CYP27B1 protein expression was not significantly different between C. jejuni-infected epithelial cells and controls, although it tended to increase during infection, particularly in the presence of VD." (PMID 34445577, 2021). "Similar to T helper cells, cytotoxic T lymphocytes (CTL) express both CYP27B1 and VDR, and upregulation of VDR can be observed in response to infection as well as mitogen stimulation, suggesting a coordinate regulation of VDR signaling pathway and CTL responses." (PMID 32679784, 2020). "In the presence of infection, activated macrophages and monocytes, induced by toll-like receptor signaling and exposure to inflammatory cytokines such as interferon-Ƴ (IFN-Ƴ), strongly express CYP27B1 which converts 25(OH)D into 1,25(OH)2D." (PMID 32679784, 2020). "Except for Hsd3b1, infection with S. haematobium did not have an influence on Vitamin D pathway associated (VDR, Cyp27b1) or immunological (IL10, IFNG, Foxp3) genes as well as vitamin D plasma levels." (PMID 31673046, 2019). "Upon infection of monocytes with M. leprae, there was no upregulation of CYP27B1 nor its enzymatic activity converting the inactive prohormone form of vitamin D (25-hydroxyvitamin D) to the bioactive form (1,25α-dihydroxyvitamin D)." (PMID 30300363, 2018). "On the other hand, CYP27B1 gene expression in IL-15 MΦ, which have high CYP27B1 gene expression at baseline, was not significantly affected as a result of either infection or stimulation with exogenous TLR2L." (PMID 30300363, 2018).
infection (continued). "Similarly, in PKDL, raised serum 25(OH)D3 was accompanied by an enhanced mRNA expression of CYP27B1, VDR and LL-37, indicating that infection upregulated the molecular switch needed for monocyte polarization towards a M2 phenotype." (PMID 26496711, 2015). "Thus, the results above from in-depth mechanistic experiments demonstrated that MIR337-3p targeted/depressed upstream TLR4/MYD88 and STAT3 signaling and the downstream VDR antimicrobial pathways of CYP27B1/DEFB4A/CAMP, leading to an enhanced mycobacterial entry/infection and growth." (PMID 34912331, 2021).
kidney disease (5 papers, 2015 to 2024). "A reduction in CYP27B1 activity occurs in kidney disease, which subsequently inhibits the production of 1,25(OH)2D3 and impairs the reabsorption of 25(OH)D." (PMID 36835159, 2023). "The decrease in CYP27B1 enzyme activity and 1,25(OH)2D3 levels can be explained by the increase in FGF-23 activity observed in the early stages of kidney disease." (PMID 36835159, 2023).
immune disorders (4 papers, 2012 to 2022). "Hou and other researchers have reported that the expression of CYP27B1 and synthetic vitamin D levels in the placenta and decidua are lower during spontaneous abortion, resulting in some placental immune disorders." (PMID 36326421, 2022). "Both VDR−/− and CYP27B1−/− mice have serious developmental problems that lead to dermatological, skeletal, reproductive and immune dysfunction." (PMID 23049920, 2012). "Given that the CYP27B1 enzyme exerts a critical role for cell specific functions, the potential to modulate 1,25(OH)2D3 production in specific tissues may improve the treatment of immune diseases." (PMID 33066266, 2020).
inflammation (3 papers, 2017 to 2023). Aberrant reaction of the microcirculation characterized by movement of fluid and leukocytes from the blood into extravascular tissues. "In conclusion, this study showed that the VDR expression decreased in the islets of Langerhans during pancreatic inflammation and demonstrated the expression of CYP24A1 and CYP27B1 in canine pancreases for the first time." (PMID 37808100, 2023).
adenocarcinoma (2 papers, 2015 to 2025). A common cancer characterized by the presence of malignant glandular cells. "In this study, we demonstrate that its precursor, 25(OH)D3, decreased cell count and viability, induced apoptotic cell death, and upregulated the gene and protein expression of VDMS enzymes (CYP27B1 and CYP24A1) and receptor (VDR) in the HeLa adenocarcinoma cell line." (PMID 40362248, 2025).